SEPTIN2 (septin 2)
Description:
Filament-forming cytoskeletal GTPase. Forms a filamentous structure with SEPTIN12, SEPTIN6, SEPTIN2 and probably SEPTIN4 at the sperm annulus which is required for the structural integrity and motility of the sperm tail during postmeiotic differentiation. Required for normal organization of the actin cytoskeleton. Plays a role in the biogenesis of polarized columnar-shaped epithelium by maintaining polyglutamylated microtubules, thus facilitating efficient vesicle transport, and by impeding MAP4 binding to tubulin. Required for the progression through mitosis. Forms a scaffold at the midplane of the mitotic splindle required to maintain CENPE localization at kinetochores and consequently chromosome congression. During anaphase, may be required for chromosome segregation and spindle elongation. Plays a role in ciliogenesis and collective cell movements. In cilia, required for the integrity of the diffusion barrier at the base of the primary cilium that prevents diffusion of transmembrane proteins between the cilia and plasma membranes: probably acts by regulating the assembly of the tectonic-like complex (also named B9 complex) by localizing TMEM231 protein. May play a role in the internalization of 2 intracellular microbial pathogens, Listeria monocytogenes and Shigella flexneri.
Synonyms: NEDD-5; DIFF6; KIAA0158; NEDD5; SEPT2; hNedd5; Pnutl3; Septin-2
Tractability: Small molecule: a structure with a bound ligand is known; it has a high-quality binding pocket. Antibody: its Gene Ontology location is reachable by antibodies, with high confidence. PROTAC: ubiquitination databases record sites on it.
Gene: Protein-coding gene on chromosome 2 (241,314,923 to 241,354,030, forward strand). Ensembl gene ENSG00000168385.
Subcellular location: Cytoplasm; Cytoplasm, cytoskeleton; Cytoplasm, cytoskeleton, spindle; Chromosome, centromere, kinetochore; Cleavage furrow; Midbody; Cytoplasm, cell cortex; Cell projection, cilium membrane; Cell projection, cilium, flagellum
Subcellular location (Human Protein Atlas): Actin filaments; Annulus; Cytokinetic bridge; Microtubules; Plasma membrane; Primary cilium; Principal piece
Pathways (Reactome):
Organelle biogenesis and maintenance: Anchoring of the basal body to the plasma membrane
Gene Ontology:
Molecular function: cadherin binding; protein binding; GTPase activity; molecular adaptor activity; enzyme regulator activity; GTP binding
Biological process: cytoskeleton organization; cilium assembly; cytoskeleton-dependent cytokinesis; intracellular protein localization; smoothened signaling pathway; cell division
Cellular component: actin cytoskeleton; axoneme; cilium; cytoplasm; extracellular exosome; intercellular bridge; microtubule cytoskeleton; non-motile cilium; nucleus; photoreceptor connecting cilium; septin complex; sperm annulus; cell cortex; cell division site; ciliary membrane; septin ring; cell surface; ciliary transition zone; cleavage furrow; cytoskeleton; midbody; motile cilium; plasma membrane; spindle; synapse
Genetic constraint (gnomAD): Loss-of-function variants: 28 observed, 38.98 expected, observed/expected ratio (o/e) 0.72, 90% interval 0.53 to 0.99. The upper end of that interval is the gene's LOEUF score, 0.99, which puts it in group 4 of 6, group 1 being the genes least tolerant of losing a copy. Missense variants: 316 observed, 426.25 expected, observed/expected ratio (o/e) 0.74, 90% interval 0.68 to 0.81. Synonymous variants: 165 observed, 148.06 expected, observed/expected ratio (o/e) 1.11, 90% interval 0.98 to 1.27.
Homologues: Orthologues: chimpanzee SEPTIN2 (100% identical), macaque SEPTIN2 (100% identical), mouse Septin2 (99% identical), rabbit SEPTIN2 (98% identical), rat Septin2 (98% identical), pig SEPTIN2 (87% identical), zebrafish septin2 (87% identical), tropical clawed frog septin2 (83% identical). Paralogues in human: SEPTIN5 (58% identical), SEPTIN1 (56% identical), SEPTIN7 (55% identical), SEPTIN3 (42% identical), SEPTIN9 (41% identical), SEPTIN11 (40% identical), SEPTIN14 (39% identical), SEPTIN6 (39% identical), SEPTIN12 (39% identical), SEPTIN8 (39% identical), SEPTIN10 (39% identical), TMEM250 (8% identical).
Diseases named in the same sentence as SEPTIN2 in open-access papers:
SEPTIN2 is named in the same sentence as 22 diseases in open-access papers, as found by Europe PMC text mining. Sharing a sentence is not in itself a finding about the gene and the disease. The quoted sentences say what the papers report.
epithelial ovarian cancer (2 papers, 2019 to 2020). "Stable septin-2 knockdown clones developed in an ovarian cancer cell line exhibited a significant decrease in proliferation rates." (PMID 31105878, 2019). "Additionally, ovarian tumor stroma has been found to be highly enriched for septin-2 and -9, prompting us to further investigate the role of these two structural proteins in ovarian cancer." (PMID 32094384, 2020). "The correlation between septin-2 expression and increased mortality was also found in kidney, lung, liver, and pancreatic cancers, but not in ovarian cancer (data not shown)." (PMID 32094384, 2020).
Cirrhosis (1 paper, 2016). A chronic disorder of the liver in which liver tissue becomes scarred and is partially replaced by regenerative nodules and fibrotic tissue resulting in loss of liver function. "We focussed on septin 2, the major ubiquitously expressed septin and the most deregulated in HCV-induced cirrhosis." (PMID 27417143, 2016).
dysgerminoma (1 paper, 2019). A malignant germ cell tumor characterized by the presence of a monotonous primitive germ cell population. "While all other histopatholgies exhibited higher mean intensity levels of septin-2—mucinous (603 pixels), clear cell (821 pixels), and dysgerminoma (744 pixels)—compared to the normal adjacent tissue, none were considered statistically significant, possibly due to low numbers of samples available." (PMID 31105878, 2019).
endometrial cancer (1 paper, 2020). Primary or metastatic malignant neoplasm involving the endometrium (mucous membrane that lines the endometrial cavity). "Analyses of The Cancer Genome Atlas (TCGA) show that both septin-2 and septin-3 overexpression correlate with increased mortality in endometrial cancer." (PMID 32094384, 2020). "We conducted Kaplan-Meier survival analyses for endometrial cancer stratified by expression of septin-2, -3, and -7." (PMID 32094384, 2020). "It is therefore not surprising that we have linked high septin-2 levels to worse patient survival in several cancer types, including endometrial cancer." (PMID 32094384, 2020). "In endometrial cancer, relative expression of septin-2 was highest, followed by septin-7." (PMID 32094384, 2020).
Hypertension (1 paper, 2017). The presence of chronic increased pressure in the systemic arterial system. "Moreover, the effect of Tianma on correcting the function and activity of Tpi1, Ppia, Ncam1, Uchl1, Septin-2 and Hsp90aa1 proteins, provided conclusive evidence for Tianma in the treatment of seizures, hypertension and headaches." (PMID 29262557, 2017).
myocardial infarction (1 paper, 2022). Gross necrosis of the myocardium, as a result of interruption of the blood supply to the area, as in coronary thrombosis. "Additionally, GWAS have associated single nucleotide polymorphisms (SNPs) in miR-140-5p gene targets such as SEPT2 (SEPTIN2) with T1DM, DNMT1 with CVD and HDAC4 with increased susceptibility to myocardial infarction following coronary artery bypass surgery." (PMID 36277770, 2022).
serous ovarian cancer (1 paper, 2019). "While our proteomics study was performed in a serous ovarian cancer cell line, it would be interesting to repeat the stable knockdown experiment in a clear cell EOC line, since septin-2 was also found to be overexpressed in this histopathology." (PMID 31105878, 2019).
cancer (7 papers, 2016 to 2024). A tumor composed of atypical neoplastic, often pleomorphic cells that invade other tissues. "In cancer-associated stroma, the expression of septin-2 and septin-9 was significantly upregulated, while septin-6 and septin-7 were unchanged." (PMID 32094384, 2020). "The Cancer Genome Atlas (TCGA) database analysis revealed that the expression of septin-2 and septins 6–11 is notably elevated in comparison to other septins." (PMID 38473335, 2024). "Collectively, these data reveal Septin 2 as a novel interacting partner and isomerase substrate of Cyclophilin A at the midbody that is required for abscission during cytokinesis in cancer cells." (PMID 37446263, 2023). "In the present study, septin-2 knockdown caused a decrease in HER2 and HE4 expression and inhibited the viability of cancer cell lines." (PMID 32094384, 2020). "Aberrant expression of septins is involved in tumorigenesis, e.g., overexpression of septin-2,-8,-9,-11 and downregulation of septin-4 and septin-10 have been identified in a wide variety of cancer types." (PMID 27525972, 2016). "Inhibition of septin-2 also decreased the viability of cancer cell lines." (PMID 32094384, 2020). "Control of MMP-9 secretion is a known anti-inflammatory effect of pioglitazone and other PPARγ ligands; they can modulate septin-2 in cancer cells preventing MMP-9 actions, and during the course of intestinal inflammations, down-modulation of PPARγ can make MMP-9 more stable." (PMID 33519451, 2020). "For instance, the filament-forming cytoskeletal GTPase SEPTIN2 is necessary for normal chromosome segregation and spindle elongation during the progression through mitosis, and its phosphorylation at S218 by protein kinase CK2 is crucial for cancer cell proliferation." (PMID 34356831, 2021).
tumor (5 papers, 2005 to 2019). "These investigations highlight that septin-2, and septins in general, play an important role in cellular proliferation and potentially promote tumor growth." (PMID 31105878, 2019). "Increased levels of septin 2, 8, 9, 11 and decreased levels of septin 4 and 10 have been consistently reported in various tumor types and are assumed to act as oncogenes and tumor suppressor genes, respectively." (PMID 29699512, 2018). "TTFields interferes with α-/β-tubulin and septin 2, 6, 7 heterotrimer function in tumor cells during mitosis." (PMID 26739692, 2016). "Since we have shown that the knockdown of septin-2 promotes irregular expression of a multitude of pathways related to mRNA and protein modifications, it seems reasonable that its downregulation would also affect tumor cell growth." (PMID 31105878, 2019). "Additionally, both in vitro and in vivo studies could be performed to confirm that inhibition of septin-2 affects cell viability and tumor growth in order to determine if targeting of septin-2 synergizes with platinum-based chemotherapeutics." (PMID 31105878, 2019). "Therefore, it can be hypothesized that the inhibition of septin-2 would exhibit a therapeutic effect in EOC via suppression of tumor metabolic pathways." (PMID 31105878, 2019). "However, there have also been numerous studies linking septin-2 to neoplasia." (PMID 31105878, 2019).
infection (1 paper, 2023). The state of being infected such as from the introduction of a foreign agent such as serum, vaccine, antigenic substance or organism. "In the infection models using mosquito cells, the double-stranded RNA (dsRNA) binding protein Loquacious, epigenetic regulator DIDO1, and septin 2 were found essential for the replication of DENV or ZIKV50–52." (PMID 37794048, 2023).
SEPTIN2 also shares sentences with these, for which no sentence is quoted: ovarian cancer (2 papers); psychosis (2); Alzheimer disease (1); Burkitt lymphoma (1); depression (1); glioblastoma (1); Hodgkins lymphoma (1); infectious mononucleosis (1); ovarian tumor (1); pancreatic cancers (1); systemic lupus erythematosus (1); systemic sclerosis (1).